UNG (uracil DNA glycosylase)
Diseases named in the same sentence as UNG in open-access papers (continued):
Sharing a sentence is not in itself a finding about the gene and the disease.
infection (12 papers, 2008 to 2023). The state of being infected such as from the introduction of a foreign agent such as serum, vaccine, antigenic substance or organism. "Viral aniPOND revealed that when infection is carried out in the presence of T2AA, the amount of viral uracil glycosylase (UNG), UL2, that associates with replicating viral DNA decreased by 4-fold compared to an uninhibited control." (PMID 37486931, 2023). "The uracil-DNA glycosylase enzyme gene “UNG” was significantly induced by BKPyV-infection (q = 0.0213)." (PMID 35194151, 2022). "The post-infection upregulation of UNG and SAMHD1 and the downregulation of dUTPase suggest a coordinated response to the invading virus." (PMID 36114511, 2022). "We measured large changes in the expression levels of UNG and two other enzymes in our panel at various times after infection of AM with R5 tropic HIVBal virus." (PMID 36114511, 2022). "The cells which were supported the productive infection of M13mpl9 phage containing uracil-DNA were used to isolate plasmid DNA which presumably carrying the gene of the potential UNG inhibitor." (PMID 34068736, 2021). "Overexpression of human uracil DNA glycosylase in MDM prior to infection resulted in rapid removal of dUMP from HIV cDNA and near complete depletion of dUMP-containing viral copies." (PMID 32663205, 2020). "We next examined the expression and activity of the vUNG upon the infection of host UNG−/− MEFs with the ORF46.stop virus (46.stop) and the ORF46.stop marker rescue (MR) virus (46.MR)." (PMID 30377280, 2018). "The first experiments leading to the discovery of an inhibitory protein against UNG were conducted in the Friedberg laboratory after they had observed that the UNG enzyme of Bacillus subtilis had lost its activity against U-DNA 4 min after the infection of the bacteria with phage PBS2." (PMID 34068736, 2021). "This led us to investigate whether infection in UNG−/− mice would reveal novel or exacerbated phenotypes for the vUNG mutant." (PMID 30377280, 2018). "Overexpression of UNG might present an advantage for the parasite in the processes and establishment of infection." (PMID 29636843, 2018). "We then used RT-qPCR to probe the base line expression levels of key UBER enzymes (UNG, APE1, pol β, lig III, DUT) and the dNTPase SAMHD1 in AM and MDM prior to infection with HIV." (PMID 36114511, 2022). "Accordingly, cell surface proteins targeted specifically by Vpu (tetherin and SNAT1) are depleted late in the time course of infection, and intracellular proteins known to be targeted by Vif (APOBEC3C) and Vpr (UNG) show distinct temporal profiles." (PMID 27690223, 2016). "Strikingly, AM showed a 20-fold induction of UNG mRNA between days 3 and 14 post infection, while no significant increases in UNG expression were observed with MDM over the same time frame." (PMID 36114511, 2022). "In addition, the increased expression of UNG and SAMHD1 in AM post-infection is too slow to prevent integration." (PMID 36114511, 2022). "To better distinguish the contribution of the viral UNG from the host UNG in the context of infection, we examined virus replication and pathogenesis in mice lacking mitochondrial and nuclear isoforms of host UNG1/2 (UNG−/−)." (PMID 30377280, 2018). "UNG activity was also detected upon infection with 46.MR, but not 46.stop." (PMID 30377280, 2018). "The infection of UNG−/− mice did not reveal a replication defect for ORF46.CM." (PMID 30377280, 2018).
adenocarcinoma (1 paper, 2015). A common cancer characterized by the presence of malignant glandular cells. "Pemetrexed-resistant sublines of H1299 adenocarcinoma cells have elevated levels of UNG, hence enhanced BER activity, and combined treatment of these H1299 sublines with MX and pemetrexed increased their sensitivity to pemetrexed." (PMID 26579709, 2015).
UNG also shares sentences with these, for which no sentence is quoted: diffuse large B-cell lymphoma (3 papers); head and neck squamous cell carcinoma (3); glioblastoma (2); hypophysitis (2); lung squamous cell carcinoma (2); pancreatic ductal adenocarcinoma (2); urothelial carcinoma (2); ataxia telangiectasia (1); autoimmune disorders (1); bladder cancer (1); cardiac hypertrophy (1); cervical squamous cell carcinoma (1); childhood leukemia (1); chronic lymphocytic leukemia (1); colorectal adenocarcinoma (1); esophageal cancer (1); Fanconi anemia (1); folate deficiency (1); hematologic cancers (1); hepatocellular carcinoma (1); HIV-1 infection (1); inflammatory bowel disease (1); leukemia (1); liver cancer (1); malaria (1); mild cognitive impairment (1); neuroblastoma (1); pancreatic cancer (1); Parkinson disease (1); renal cell carcinoma (1).
A further 5 diseases each share a sentence with UNG in 1 paper.